CD4 (CD4 molecule)
Diseases named in the same sentence as CD4 in open-access papers (continued):
Sharing a sentence is not in itself a finding about the gene and the disease.
Salmonella Infections (continued). "The study hypothesizes that Salmonella infection induces CD4+CD25+ T regulatory cells and suppresses host T cells locally in the gut to escape the host immune responses." (PMID 34843525, 2021). "CD4 T cells are typically identified as the most important effector cells following Salmonella infection, and we show that our immunization, which mimics a natural route of infection, induces a vaccine-specific CD4 T-cell response in the spleen, and mLNs that increases when OMVs are included." (PMID 34069796, 2021). "Following Salmonella infection, the Th17 response in the CD4+ T cell population shifts to a Th1-biased response, and IL-17A, which is increased by Salmonella infection, stimulates intestinal epithelial cells to enhance the production of antimicrobial proteins and chemokines." (PMID 34484221, 2021). "HIV infection and decreased CD4+ T‐cell counts correlate with susceptibility to invasive nontyphoidal Salmonella infection rather than disease with typhoidal strains." (PMID 33005416, 2020). "Here, we hypothesized that CD4+ recent thymic emigrants are essential immune mediators during persistent Salmonella infection." (PMID 32722409, 2020). "Thymic output may especially be important during Salmonella infection, where CD4+ T cells have been shown to be essential for resistance against both acute and persistent infection." (PMID 32722409, 2020). "Using T cell-specific Fbxo7 deficient mice (Fbxo7tm1c/tm1c; CD4-Cre+) we repeated the Salmonella infection but observed no weight loss phenotype indicating that there is no role of FBXO7 within mature peripheral T cells for the phenotype observed." (PMID 30840666, 2019). "T cells, and CD4+ T cells in particular, play a critical role in combatting Salmonella infection." (PMID 28584281, 2017). "Thus, flagellin is a well-defined target antigen of CD4+ T-cells during Salmonella infection and this response contributes modestly to protective immunity in vivo." (PMID 25566242, 2014). "Moreover, a lack of IL-35 production by B cells led to increased activation of macrophages and CD4+ Th1 cells and favored B cells as APCs in a Salmonella infection model." (PMID 25484884, 2014). "Thus, polyfunctional CD4+ T cells that develop during Salmonella infection produce simultaneously IFN-γ, TNF and IL-2 and the differential amounts of IFN-γ that is being produced by these cells correlates with the immunodominance hierarchy." (PMID 22912884, 2012). "Together these data establish the tempo of persistent infection, the accompanied activation status of the T cells, and the importance of CD4+ T cells in our experimental virulent Salmonella infection model and reflects the findings of other Salmonella infection models." (PMID 22912884, 2012). "The identification of differential cytokine expressing CD4+ T cells could lead to novel predictors of disease activity of virulent Salmonella infection as has recently been found for other pathogens such as HIV and Mycobacterium tuberculosis." (PMID 22912884, 2012). "The requirement for CD4+ T cells in bacterial clearance during persistent Salmonella infection may reflect contributions from either Foxp3-negative effector or Foxp3+ regulatory T cells (Tregs)." (PMID 20714351, 2010). "Furthermore, our findings suggest that CD4+ T cells may contribute to immune compensation in TCR Cγ−/− chickens during Salmonella infection." (PMID 40438105, 2025). "Seung-Joo Lee and colleagues also found a significant increase in PD-L1 on CD4+ T-cells during Salmonella infection and that PD-L1-deficiency did not affect specific antibody production and CD4+ T-cell expansion but affected CD4+ T-cell maturation and function." (PMID 35663968, 2022). "Since Salmonella infection results in a massive cytokine storm in the intestinal mucosa, we hypothesized that infection-induced cytokines would potentially be required to efficiently stimulate IL-22 production from Th22 or related CD4+ cell subpopulations." (PMID 34566952, 2021).
Salmonella Infections (continued). "Given that testosterone enhances CD4+ and CD8+ T cells and CD4+ T cells are also highly important in protection against Salmonella infection (Mittrücker & Kaufmann, 2000), the sex difference in Salmonella load in our study may be explained by differences in steroid hormone concentrations." (PMID 26949230, 2016). "Similar to Salmonella infection, the mechanistic basis of this arrested immunity is largely unknown but can be mitigated by delaying the start of antibiotic treatment, presumably because this allows more time for CD4 T cell memory to develop." (PMID 27999159, 2016). "Our finding that the frequency of immunodominant Salmonella-specific CD4+ T cell responses can be used as an immunological predictor for the disease activity opens new avenues for diagnosis of Salmonella infection and may aid in the rational design of vaccines." (PMID 22912884, 2012). "Although blocking of IL-10 in vivo and ex vivo led to a better Salmonella infection control in our model, the complex interplay of iron excess and the absence of TIM-3 signalling and their influence on the function of CD4+ CTL warrants further investigation." (PMID 40939292, 2025). "Next, since both CD4+ and CD8+ T cells are crucial for protection against Salmonella infection, we evaluated T cell subtypes induced by ATOMSal-L6 vaccination." (PMID 35898510, 2022). "Together, these data suggest that CD4 T cell IFN-γ production during Chlamydia infection is largely T-bet-independent and contrasts sharply with the response to Salmonella infection." (PMID 35196366, 2022). "We found that S. Infantis induces an increase in the proportion of proinflammatory CD4+ IFNγ+ T cells in Peyer’s patches in pigs; however, little is known regarding the roles of CD4+/− CCR6+/− T cells or CCR6+/− IFNγ+/− T cells during Salmonella infection." (PMID 32093767, 2020). "The production of CD4 and CD8 T cells as part of an adaptive cellular immune response is crucial for the clearance of Salmonella infection in mice." (PMID 28143524, 2017). "The role of the Th1 subset of CD4 T cells and its effector cytokine IFN-γ in Salmonella infections has been very well established, making Salmonella model systems particularly appropriate for characterizing Th1 cell functions." (PMID 25540644, 2014). "The host immune response against Salmonella infection requires the induction of a CD4 type 1 Helper T cell or TH1 immune response, involving CD4 T cells expressing the transcription factor T-bet." (PMID 23754944, 2013). "To examine the importance of activated CD4+ and CD8+ T cell populations for controlling virulent Salmonella infection, we selectively depleted these subsets by using depleting monoclonal antibodies." (PMID 22912884, 2012). "Cellular immune responses, including CD4 and CD8-mediated interferon-γ responses, play a critical role in clearing and controlling systemic Salmonella infections." (PMID 21666798, 2011). "These analyses have shown that CD4+ and CD8+ T cells are critical to the development of protective immunity to Salmonella, and control of Salmonella infection involves prominent expression of interferon-γ by both CD4 and CD8 cells." (PMID 21666798, 2011). "The main factor of CD4+ T cell help seems to be IL-2, since replacement of CD4+ T cell help by addition of IL-2 is sufficient to elicit CD8+ T cell proliferation, induced by Salmonella infection of the B cells." (PMID 20885961, 2010). "We noted a significant increase in the percentage of CD4+ cells co-expressing CD25 in the Peyer's patch of animals fed B. infantis, particularly following Salmonella infection." (PMID 18670628, 2008). "Indeed, CD4 T cell production of IFN-γ to both Chlamydia and Salmonella infection was similar, reinforcing the concept that both of these bacterial infections drive strong Th1 responses." (PMID 35196366, 2022). "However, the precise roles played by CD4+/− CCR6+ T cells and their cytokines in response to Salmonella infection remain to be elucidated." (PMID 32093767, 2020).
Salmonella Infections (continued). "The requirement for a functional T cell compartment is also evidenced by the increased risk of invasive nontyphoidal Salmonella infections in humans with HIV, with lower CD4+ T cell counts correlating with greater risk." (PMID 32591391, 2020). "After Salmonella infection, the amount of IL-4 and IL-21 was strongly upregulated in CD4+ T cells of MyD88−/−, but not MyD88+/+, mice." (PMID 29973931, 2018). "Our results suggest that LGG excludes pathogens and promotes mucosal immunity to Salmonella infection through expansion of CD4+ T-bet+ IFNγ+ T cells, elevation of T-bet levels, and activation of the IL-22BP–IL-22–STAT3 pathway." (PMID 28770173, 2017). "Infected mice treated with the W6 MAb had significantly lower 2W-specific CD4+ T cells, higher bacterial burden, and did not clear the Salmonella infection." (PMID 27292946, 2016). "Unlike Salmonella infection, the antigenic targets of the CD4 response appear to be similar in mucosal and systemic locations and Th1 cells were primarily detected both locally and systemically." (PMID 25071779, 2014). "The relevance of these mechanisms in vivo is not clear as CD4+ T-cell priming has also been observed in mouse models of Salmonella infection." (PMID 23319341, 2013). "Thus, although both CD4+ and CD8+ T cell subsets are activated, CD4+ T cells play a particular important role in the control of virulent Salmonella infection." (PMID 22912884, 2012). "It is possible that Salmonella induce CD4 degradation in a similar way as suggested by the observation of the lack of CD4 positive DCs at 5 days post-Salmonella infection in B cell follicle borders in the spleen." (PMID 23284947, 2012). "In addition, B cells are involved in the generation of a profound CD4+ and CD8+ T cell response after Salmonella infection, but the precise role of B cells remained unclear." (PMID 20885961, 2010). "Notably, while Salmonella infection did not largely affect the frequencies of RORγt+FoxP3- CD4 T cells in the cecum, their absolute abundance was 2.5-fold higher in eSPF+SFB after infection compared to steady state conditions." (PMID 34566952, 2021). "Nevertheless, is important to recall that despite the rapid development of a large number of CD4+ T-cells during primary Salmonella infection, there is actually very little evidence to suggest that, at this early stage of infection, they contribute to bacterial clearance." (PMID 33822791, 2021). "Moreover, unlike Salmonella infection CD4+ T cells from the SI also released IL-22 upon ex vivo restimulation suggesting that these cells also reside in the SI." (PMID 34566952, 2021). "We found that, indeed, thymectomized adult mice could not control persistent Salmonella infection despite a surprising, and significant, increase in peripheral Salmonella-specific CD4 T cells." (PMID 32722409, 2020). "Having established that OX40L expression by ILC3s was not required in the response to Lm-2W1S, the Salmonella infection model provided an opportunity to further test the potential role of ILC3s in supporting CD4 T cells at mucosal sites via their expression of OX40L50." (PMID 32647184, 2020). "The epitopes within the type III secretion system proteins were discovered using a non-virulent Salmonella model and the CD4+ T cell responses to these epitopes in this model displayed similar kinetics as compared to the EutC243–257-specific response during virulent Salmonella infection." (PMID 22912884, 2012). "To ascertain whether there was a difference between thymectomized or sham control mice at baseline, we measured the number of both 2W1S-specific and total CD4+ T cell numbers in thymectomized and sham surgical control mice in the absence of Salmonella infection." (PMID 32722409, 2020).
Salmonella Infections (continued). "Together, these data suggest that, during Salmonella infection, non-cognate signals may be vitally important for driving CD4 Th1 and CD8 T cells to produce IFN-γ and that mice lacking these particular pathways may be unable to generate an effective adaptive response." (PMID 25071779, 2014). "We characterized the activation and memory state of SFB-induced IL-17A and/or IL-22 producing CD4+ T cells based on the expression of specific markers including CCR6, CD44, and CD62L in the presence or absence of Salmonella infection." (PMID 34566952, 2021). "While the protective contribution of distinct T cell memory subsets has not been fully explored in Salmonella infection models, recent data demonstrate that TRM CD4 T cells are critically important for immunity to Chlamydia infection." (PMID 27999159, 2016). "The data thus far suggest that differences in DC subset abundance or CD80/86 expression on DCs, as well as CD4+ or CD8+ T cell numbers in infected tissues, do not explain the observed difference in survival of the mouse strains to Salmonella infection." (PMID 26441965, 2015). "The observed increase in the IL-1β and IFNγ mRNA of CD4+CD25- cells occurred only in the internal organ but not in the cecal tonsils, suggesting that the systemic host immune response to Salmonella infection differs from the mucosal immune response to Salmonella." (PMID 34843525, 2021). "Besides, they identifiy that SFB induces, in the context of the eSPF microbiota, the acquisition of diverse cytokine-production profiles in CD4+ T cells, including a subset that produces IL-22 but not IL17A after Salmonella infection." (PMID 34566952, 2021).
Chagas disease (66 papers, 2006 to 2026). A parasitic infection caused by Trypanosoma cruzi. "Signs of senescence, the later stages of differentiation, the effects of immunoregulatory mechanisms and the expression of inhibitory receptors associated with more severe forms of Chagas disease have also been described in the CD4+ T-cell population." (PMID 33539379, 2021). "Signs of senescence and the late stages of differentiation associated with the more severe forms of Chagas disease have been described in the Trypanosoma cruzi antigen-specific CD4+ T-cell population." (PMID 33539379, 2021). "Our findings reveal a novel association between increased GRAIL expression and impaired CD4 T cell proliferation during Trypanosoma cruzi infection." (PMID 28114324, 2017). "We have previously shown that thymic atrophy during acute experimental Chagas disease ischaracterized by a massive loss of CD4+CD8+ thymocytes, beingrelated to the pro-apoptotic action of increased levels of circulating GCs." (PMID 24324845, 2013). "CD4+ T cells from Chagas disease patients carrying DERAA-DRB1 alleles show increased expression of cytotoxic, chemotactic, and proapoptotic genes, whereas patients carrying non- DERAA-DRB1 alleles show upregulation of survival, antiapoptotic and anergy-related genes." (PMID 40391216, 2025). "In favor of this hypothesis, the role of CD4+ cytotoxic T-cells has been shown in the murine model of Chagas disease, and has been markedly associated with human Chagas cardiomyopathy." (PMID 40391216, 2025). "Finally, and importantly, we detected the presence of CD4+ T cells expressing perforin in the blood of patients with the severe cardiac form of Chagas disease and correlation analyses point to a possible pathogenic role of these cells in the chronic phase of Chagas myocarditis." (PMID 35670567, 2022). "As a result, the study of Chagas disease in immunosuppressed patients reveals the association of a defective immune system with the lack of control of T. cruzi infection, as is the case in patients with low CD4+ T-cell counts who have a high parasitic load, which is linked to coinfection with HIV." (PMID 33539379, 2021). "The CD4+CD8+ T cell exhaustion process observed in chronic chagasic patients could be associated with the T. cruzi antigenic persistence that occurs during the chronic phase of Chagas disease." (PMID 29750791, 2018). "We found compelling evidence that hypoxia modulates the CD4 T-cells with cytotoxic potential by triggering, in a time-dependent manner, purinergic signaling during Trypanosoma cruzi infection." (PMID 40590226, 2025). "Remarkably, it has been demonstrated that CD4+ T-cells from Chagas disease patients possess the ability to proliferate when exposed to the P214-cruzipan epitope, which exhibits structural similarity to the catalytic domain of cathepsin S." (PMID 40391216, 2025). "These parasite-derived peptides are capable of activating diverse subsets of CD4+ T-cells, particularly IFN-γ+CD4+ T-cells in severe cases of Chagas disease, upon stimulation by members of the trans-sialidase superfamily." (PMID 40391216, 2025). "Despite the acknowledged role of cytotoxic T cells in the pathogenesis of Chagas disease, the contributions of CD4+ T cells and B cells are less understood, likely due to their ability to interfere with other immune cells’ function." (PMID 38726014, 2024). "Taken together, CD4+ T cells from patients with Chagas disease bear an effector and activated phenotype that is pronounced in the mild CCC clinical form." (PMID 38726014, 2024). "Here, we employed high-dimensional flow cytometry to analyze CD4+ T and B cell compartments in patients during the chronic phase of Chagas disease, presenting the asymptomatic and mild or moderate/severe cardiac clinical forms." (PMID 38726014, 2024).